JMJD6 (jumonji domain containing 6, arginine demethylase and lysine hydroxylase)
Diseases named in the same sentence as JMJD6 in open-access papers (continued):
Sharing a sentence is not in itself a finding about the gene and the disease.
tumor (continued). "Since both JMJD6 and EZH2 associate independently with poor prognosis in cancer, the results were extrapolated to clinical samples, and their expression and association was studied in tumor and normal samples; and in publicly available RNA-Seq databases." (PMID 33246425, 2020). "Treatment with THZ1 or panobinostat alone reduced tumor growth in mice xenografted with empty vector SK-N-AS cells and treatment with panobinostat alone reduced tumor growth in mice xenografted with SK-N-AS cells transfected with JMJD6 ORF." (PMID 31346162, 2019). "Additionally, when overexpressed in MMTV-Myc-driven tumor cells that lack the 11q amplification, JMJD6 induces EMT, increases cell migration and invasion in vitro, and stimulates tumor growth in vivo." (PMID 27081402, 2016). "Since U2AF65 is hydroxylated by JMJD6, we can speculate that the overexpression of JMJD6 may increase angiogenesis via its hydroxylase activity, in order to promote tumor proliferation." (PMID 27556302, 2016). "Also, we found that JMJD6 deprivation increased cell migration of tumour cells analysed by wound scratch test." (PMID 25951181, 2015). "Interestingly, there were significant positive correlations between JMJD6 expression and depth of invasion (p<0.05), lymph node metastasis (p<0.05), and advanced tumor node metastasis (TNM) stage (p<0.01)." (PMID 24667498, 2014). "However, the mechanism of JMJD6 as a tumor-associated protein in ESCC is not sufficient, which need more researches to be further elucidated." (PMID 37488513, 2023). "However, it remains incompletely defined whether and trough which mechanism JMJD6 regulates the activation of TAMs and the tumor microenvironment." (PMID 37567973, 2023). "Based on these results, we speculated that JMJD6 might play a tumor-promoting role in ESCC." (PMID 37488513, 2023). "Sections of colon tissue that is known to express JMJD6 were used as a positive control, and sections of thymic tissue that is negative for JMJD6 were used as a negative control, and each staining pattern in IHC intensity score (0/1/2/3) of tumor-adjacent normal/cancer tissue is shown." (PMID 37488513, 2023). "In addition, tumor-CM effectively upregulated JMJD6 expression in both BMDMs and PMs of mice." (PMID 37567973, 2023). "However, how JMJD6 regulates immune inflammatory factors through epigenetic modification to affect tumor development, and whether JMJD6-mediated arginine demethylation and lysine hydroxylation affect tumor immunotherapy are unclear." (PMID 35359945, 2022). "JMJD6 is upregulated in several types of cancer; it is natural to speculate that JMJD6 overexpression-mediated inhibition of DNA repair may be one of the reasons for the increased genomic instability of tumor cells." (PMID 31358914, 2020). "Therefore, we conclude that JMJD6 is a marker for tumor aggressiveness and maybe is prognostic of poor outcome in ER+ breast cancer." (PMID 22621393, 2012). "Their interaction and positive feed-forward loop, perpetuated by JMJD6 and YBX1 inter-regulation, culminates in HOTAIR induction, which in turn is known to drive tumour progression." (PMID 40855961, 2025).
tumor (continued). "It was found that CCNB2 knockdown appreciably constrained the tumorigenic activity of the cells, while JMJD6 and PFTα reversed the effect of CCNB2 to increase the tumor size in the mice." (PMID 38166895, 2024). "To further validate the JMJD6 protein level in ESCC tissues, we detected JMJD6 expression using IHC analysis in a tissue microarray containing 141 paired ESCC tumor-normal tissues." (PMID 37488513, 2023). "Compared with tumor cells (CD45−) and other immune cells (CD45+ F4/80−), TAMs (CD45+ F4/80+) exhibited higher JMJD6 expression." (PMID 37567973, 2023). "The genetic inhibition of JMJD6 decreased ANXA1 expression, preventing M2 polarization of macrophage and tumor aggressiveness." (PMID 37567973, 2023). "Using tumor tissue and corresponding paracancerous samples from 141 resected ESCC patients, we assessed Jumonji domain-containing protein 6 (JMJD6) expression using Immunohistochemical (IHC) staining." (PMID 37488513, 2023). "JMJD6 promotes the M2 activation and protumoral activities of macrophages, thereby establishing an immunosuppressive TME favoring tumor growth." (PMID 37567973, 2023). "Inhibition of JMJD6 depressed the expression of E2F2, n-Myc and c-Myc, restrained cell proliferation in vitro and tumor growth in vivo and accelerated cell apoptosis." (PMID 35359945, 2022). "Therefore, we speculated that GNA14 inhibited tumor invasion and migration by inhibiting JMJD6." (PMID 33500727, 2021). "Importantly, THZ1 and panobinostat combination therapy synergistically reduced tumor progression and resulted in tumor regression in mice xenografted with empty vector SK-N-AS cells, but only moderately suppressed tumor progression in mice xenografted with SK-N-AS cells transfected with JMJD6 ORF." (PMID 31346162, 2019). "Consistent with these in vitro data, knocking down JMJD6 reduces E2F2 and Myc expression, suppresses tumor progression, and improves survival in mice." (PMID 31346162, 2019). "The Wilcoxon matched-pair signed rank test results further confirmed the significant upregulation of JMJD6 in tumor tissues compared with their noncancerous counterparts." (PMID 41320721, 2025). "As detected by IHC, JMJD6 expression was significantly upregulated in tumor tissues compared with their paired adjacent noncancerous tissues (NAT)." (PMID 41320721, 2025). "At the end of the experiment, Jmjd6+/− mice treated with PD-1 blockade developed a smaller number of lung metastasis foci, whereas PD-1 blockade failed to induce significant tumor inhibition in WT mice." (PMID 37567973, 2023). "To further figure out the oncogenic role of JMJD6 in RCC, we analyzed several cohorts to evaluate its clinical significance and found that JMJD6 was commonly higher in tumor samples than in normal tissues from the TCGA‐KIRC cohort, GSE40435, GSE53757, and IGC‐RCC cohort." (PMID 33634984, 2021). "Although precise mechanisms by which JMJD6 promotes tumorigenesis and tumour progression have not been elucidated, it has been well established that interaction of JMJD6 with other cancer‐related signalling pathways is one of the underlying mechanisms." (PMID 31961032, 2020). "The CLO Lipo treatment was also found to delay tumor growth and decrease the foci number of pulmonary metastasis in WT mice, which could not be observed in Jmjd6+/− mice." (PMID 37567973, 2023). "In summary, we found that in non-tumorigenic mouse epithelial cells, JMJD6 may collaborate with c-Myc to initiate tumor formation by suppressing Myc-induced cell death by inhibiting transcriptional expression of the p19ARF tumor suppressor protein." (PMID 27081402, 2016). "This was observed in 8/10 tumours, although it was never observed with the control cells, suggesting that JMJD6 could be involved in tumour migration." (PMID 25951181, 2015).
tumor (continued). "However, our observations regarding JMJD6 (jumonji domain-containing 6, arginine demethylase and lysine hydroxylase) indicate that intron 6 APA-driven short isoform expression is almost exclusively observed in tumor samples, whereas both long and short isoforms are expressed in normal tissues." (PMID 39349823, 2024). "Immunohistochemistry staining for CD44, TGF-β, and VEGFA1 was performed in lung tissues of A549 tumor-bearing mice, which revealed that regardless of RT, JMJD6-knockdown tumors had decreased positivity of CD44, TGF-β1 and VEGFA1 compared with control tumor." (PMID 41320721, 2025). "Pearson and Spearman correlation tests revealed significant overall correlation between JMJD6 and EZH2 in both normal and tumor samples irrespective of the tumor histopathology (DCIS, IDC1 to IDC3) or molecular subtype (TNBC versus non-TNBC)." (PMID 33246425, 2020).
cancer (48 papers, 2010 to 2025). A tumor composed of atypical neoplastic, often pleomorphic cells that invade other tissues. "Our findings reveal a cancer-promoting metabolic program is associated with alternative pre-mRNA splicing through JMJD6, providing a rationale to target JMJD6 as a therapeutic avenue for treating MYC-driven cancers." (PMID 38488852, 2024). "HT and smoking are typical risk factors not only for vascular diseases, but also for cancers, which aligns with the elevated s-JMJD6-Ab levels in patients with cancers." (PMID 38732153, 2024). "Together these data raise the possibility that higher JMJD6 expression predisposes ER+ cancers to endocrine therapy resistance." (PMID 36419768, 2022). "Jumonji domain-containing 6 (JMJD6) is a candidate gene associated with tumorigenesis, and JMJD6 overexpression predicts poor differentiation and unfavorable survival in some cancers." (PMID 31637004, 2019). "JMJD6 has been linked to cancer, and its hydroxylase activity is linked to preeclampsia via regulation of the HIF system in the placenta." (PMID 31147442, 2019). "Clinically, the association between aberrant expression of JMJD6 and aggressive cancer disease with poorer prognosis prompted further investigation to understand its role in tumorigenesis." (PMID 28587176, 2017). "JMJD6 is an enzyme with pleiotropic functions that has been recently implicated in the breast, and some other cancers where high expression of JMJD6 was an indicator of poor prognosis." (PMID 27081402, 2016). "And although some of these processes have only recently been uncovered, the association between JMJD6 dysregulation and cancer has already been reported." (PMID 27556302, 2016). "We report herein that perturbation of JMJD6 expression modulates cell proliferation and cell scattering and motility: phenotypes associated with cancer metastasis." (PMID 22621393, 2012). "However, loss of JMJD6 promotes rapid recovery of cell cycle checkpoints and improvement of cell survival rate after irradiation in distinct human cancer cell lines." (PMID 35359945, 2022). "Correspondingly, JMJD6 has been implicated in various pathological states including cancers." (PMID 29187213, 2017). "Consistently, JMJD6 has been implicated in various pathological states including cancers." (PMID 29187213, 2017). "The s-JMJD6-Ab levels may be more closely associated with EC and GC than other cancer types." (PMID 38732153, 2024). "Given the important role of JMJD6 in cancer progression, we suggest that investigating JMJD6 may become an attractive diagnostic and prognosis biomarker and potential strategy to develop novel cancer therapeutics." (PMID 37488513, 2023). "The new assays will help development of small-molecule JMJD6 inhibitors for functional assignment studies and as potential cancer therapeutics." (PMID 40046450, 2025). "Particularly, JMJD6, which is located on 17q25 and is amplified in a number of cancer types, physically interacts with a subset of splicing factors such as RBM39 and regulates the alternative splicing of metabolic genes." (PMID 38488852, 2024). "Further, we show that JMJD6 is correlated with the anti-cancer activity of indisulam, a ‘molecular glue’ that degrades the splicing factor RBM39." (PMID 38488852, 2024). "Here, we show that the short and long JMJD6 APA isoforms have opposing functions in cancer cell behaviors." (PMID 39349823, 2024). "Our findings demonstrate a new mechanism by which JMJD6 coordinates metabolic programs and alternative pre-mRNA splicing, providing a rationale to target JMJD6 as a therapeutic target for MYC-driven cancers." (PMID 38488852, 2024). "The genome-wide RNA binding by JMJD6 in cancer cells and normal cells coupled with isotope labeling to dissect the metabolic effect of JMJD6 will enhance our understanding of the biological functions of JMJD6, awaiting future studies." (PMID 38488852, 2024).
cancer (continued). "Previous studies have highlighted the role of JMJD6 in cancer, and its interactions with viruses are also gradually being uncovered." (PMID 39501382, 2024). "The first JMJD6 inhibitor SKLB325 and its role in cancer were reported in 2019, and until now, few studies focused on the application of JMJD6 inhibitor in cancer." (PMID 37880710, 2023). "JMJD6 was found to be an oncogenic factor in many cancers, and MJD4 is considered one of its metabolites." (PMID 37600577, 2023). "In order to find new biomarkers for early diagnosis and prognosis, we comprehensively analyzed the clinical value and prognostic role of JMJD6 in a variety of cancers, especially in ESCC by mining the database." (PMID 37488513, 2023). "Studies on the inhibition of the human 2‐oxoglutarate dependent oxygenase JMJD6, which is a cancer target, by 2‐oxoglutarate mimics / competitors, including human drugs, drug candidates, and metabolites relevant to cancer are described." (PMID 34581506, 2022). "JMJD6 has since become an important prognostic marker and a viable therapeutic target across multiple cancers." (PMID 36419768, 2022). "Given the importance of epigenetic function in tumors, targeting JMJD6 gene by modulating the role of immune components in tumorigenesis and its development will contribute to the development of a promising strategy for cancer therapy." (PMID 35359945, 2022). "Selective for human oxygenases: 2‐Oxoglutarate‐dependent oxygenases such as JMJD6 are targets for treatment of diseases including cancer and anemia." (PMID 34581506, 2022). "The potency of JMJD6 inhibition by TCA and related intermediates, whose concentrations are sometimes elevated in cancer, was moderate at most, with fumarate being the most potent of these compounds identified as inhibiting JMJD6." (PMID 34581506, 2022). "Based on the immunomodulatory effect of JMJD6, combination therapy, such as JMJD6 inhibitors combined with immunomodulators, can also maximize the treatment efficiency of cancer patients and reduce drug resistance." (PMID 35359945, 2022). "Considering the vital role of JMJD6 in cancer treatment, researchers have investigated only one highly selective inhibitor, SKLB325, developed on the basis of the jmjC domain crystal structure." (PMID 33634984, 2021). "A GO analysis suggested that the top 300 DEGs were significantly enriched in cell growth, cell cycle, apoptotic signaling pathways, and pathways in cancer categories, implying an oncogenic role of JMJD6 in RCC." (PMID 33634984, 2021). "Continued efforts to elucidate the physiological functions of JMJD6 and the mechanisms by which JMJD6 promotes cancer progression are also critical." (PMID 31961032, 2020). "Overall, considering the role of JMJD6 in cancer progression, we believe that targeting JMJD6 is a potential strategy for developing novel therapeutics for cancer management." (PMID 31961032, 2020). "Not surprisingly, JMJD6 has been demonstrated to be upregulated in a wide spectrum of human cancers, and the enzymatic activities of JMJD6 have been shown to be related to its role in cancer." (PMID 31961032, 2020). "In the present review, we summarized the structure and functions of JMJD6, with particular emphasis on the role of JMJD6 in cancer progression." (PMID 31961032, 2020). "Contrarily, overexpressing JMJD6 increases both the CSC traits and the numbers of CSCs, which suggests that JMJD6 is a prominent modulator of the cancer stem cell phenotype and genesis in OSCC." (PMID 32280305, 2020). "Our study uncovers a novel function of JMJD6 in H4K16ac regulation and DNA damage response, and suggests a molecular mechanism for how overexpression of JMJD6 leads to increased genomic instability, thus promoting cancer development." (PMID 31358914, 2020). "Recent studies also indicate that expression of JMJD6 in some human cancers, such as lung adenocarcinoma, breast ductal carcinomas, and colon adenocarcinomas, is evidently upregulated." (PMID 31637004, 2019).